ECI2 (enoyl-CoA delta isomerase 2)
Description:
Able to isomerize both 3-cis and 3-trans double bonds into the 2-trans form in a range of enoyl-CoA species. Has a preference for 3-trans substrates.
Synonyms: pECI; DRS1; HCA88; ACBD2; DRS-1; dJ1013A10.3
Tractability: Small molecule: it has a high-quality binding pocket. PROTAC: ubiquitination databases record sites on it; its protein half-life has been measured.
Gene: Protein-coding gene on chromosome 6 (4,115,685 to 4,135,597, reverse strand). Ensembl gene ENSG00000198721.
Subcellular location: Mitochondrion (Isoform 1); Peroxisome matrix (Isoform 2)
Subcellular location (Human Protein Atlas): Mitochondria; Peroxisomes
Pathways (Reactome):
Metabolism: Beta-oxidation of very long chain fatty acids
Protein localization: Peroxisomal protein import
Gene Ontology:
Molecular function: protein binding; delta(3)-delta(2)-enoyl-CoA isomerase activity; fatty-acyl-CoA binding
Biological process: fatty acid beta-oxidation
Cellular component: membrane; mitochondrion; peroxisomal matrix; peroxisome; cytosol
Genetic constraint (gnomAD): Loss-of-function variants: 27 observed, 39.22 expected, observed/expected ratio (o/e) 0.69, 90% interval 0.51 to 0.95. The upper end of that interval is the gene's LOEUF score, 0.95, which puts it in group 4 of 6, group 1 being the genes least tolerant of losing a copy. Missense variants: 468 observed, 496.47 expected, observed/expected ratio (o/e) 0.94, 90% interval 0.87 to 1.02. Synonymous variants: 168 observed, 181.68 expected, observed/expected ratio (o/e) 0.92, 90% interval 0.81 to 1.05.
Homologues: Orthologues: chimpanzee ECI2 (98% identical), macaque ECI2 (93% identical), pig ECI2 (73% identical), dog ECI2 (73% identical), mouse Eci2 (73% identical), rat Eci2 (70% identical), guinea pig ECI2 (65% identical), tropical clawed frog eci2 (60% identical), zebrafish eci2 (59% identical), rat Eci2 (59% identical), mouse Eci3 (53% identical), Caenorhabditis elegans acbp-1 (10% identical), and 1 more. Paralogues in human: ACBD5 (17% identical), ACBD4 (15% identical), DBI (10% identical), ACBD7 (9% identical).
Diseases named in the same sentence as ECI2 in open-access papers:
ECI2 is named in the same sentence as 17 diseases in open-access papers, as found by Europe PMC text mining. Sharing a sentence is not in itself a finding about the gene and the disease. The quoted sentences say what the papers report.
prostate carcinoma (8 papers, 2017 to 2025). A carcinoma that arises from epithelial cells of the prostate gland. "Knockdown of ECI2 had minimal effect on gene expression in a cell line representing normal prostate epithelium but resulted in down-regulation of cell cycle-associated genes in prostate cancer cells." (PMID 28415728, 2017). "Studies indicate that ECI2 serves as a reliable prognostic biomarker in both ovarian and colon cancers and promotes tumor cell proliferation in prostate cancer." (PMID 40432805, 2025). "Enoyl‐CoA‐(Δ) isomerase 2 (ECI2) is involved in fat metabolism, which can promote the development of prostate cancer." (PMID 39491527, 2024). "A few studies have reported that the up-regulation of ECI2 which is considered as a downstream target of androgen receptor promotes prostate cancer progression and inhibits cell death response through lipid degradation." (PMID 37535601, 2023). "The results of our study, compared to the only two previous studies concerning ECI2 in prostate cancer, similarly found an overexpression of ECI2 in the PC group, which was statistically significant in contrast to the low expression in AH samples." (PMID 32873863, 2020). "Since ECI2 was over-expressed in prostate cancer patient samples, we moved on to assess AR-dependent regulation of this gene." (PMID 28415728, 2017). "In this study, we showed that ECI2, an enzyme involved in degradation of unsaturated lipids, is a direct AR-target and over-expressed in clinical prostate cancer." (PMID 28415728, 2017). "Integration of the RNA-seq data with metabolomics data revealed that inhibition of ECI2 expression led to acute metabolic stress in prostate cancer cells." (PMID 28415728, 2017). "Similar to ECI2 knockdown, prostate cancer cells responded by activation of incomplete autophagy, as measured by prominent accumulation of autophagy markers LC3 and adaptor protein p62." (PMID 28415728, 2017). "Since AR activity and lipid metabolism appear important in prostate cancer, here we investigate ECI2, an AR-target gene." (PMID 28415728, 2017). "ECI2 was identified as a putative AR target gene in castration-resistant prostate cancer tissue samples using ChIP-seq technology." (PMID 28415728, 2017). "In order to better understand metabolomics data, we performed RNA-sequencing after ECI2 knockdown in the LNCaP prostate cancer cell line and RWPE-1 cell line, which represents normal prostate epithelial cells." (PMID 28415728, 2017). "Here we show that Enoyl-CoA delta isomerase 2 (ECI2) is a novel AR-target that promotes prostate cancer cell survival." (PMID 28415728, 2017). "Inhibition of ECI2 expression decreased the growth rate and activated cell death response in prostate cancer cells." (PMID 28415728, 2017). "We show that ECI2 is over-expressed in prostate cancer patient samples in mRNA and protein levels, and that increased expression predicts poor outcome." (PMID 28415728, 2017). "As the first step, we evaluated ECI2 expression in matched benign and prostate cancer patient tissue samples, and observed a 2-fold increased expression of ECI2 mRNA (p = 0.024)." (PMID 28415728, 2017). "ECI2 knockdown strongly inhibited proliferation of LNCaP prostate cancer cell line but had only modest effects on RWPE-1, a cell line derived from normal prostate epithelium." (PMID 28415728, 2017). "Taken together, these data suggest that a novel AR target gene, ECI2, supports aberrant metabolic homeostasis of prostate cancer cells." (PMID 28415728, 2017). "In order to get a clearer picture of the prostate cancer cell metabolome after ECI2 knockdown, we used mass spectrometry-based untargeted metabolite profiling of intra-cellular metabolites." (PMID 28415728, 2017). "The high expression of ECI2 was proposed to be a potential therapeutic target in prostate cancer." (PMID 37535601, 2023).
prostate carcinoma (continued). "Similarly, 2,4-dienoyl-CoA reductase (DECR1) and enoyl-CoA delta isomerase 2 (ECI2), auxiliary enzymes responsible for the degradation of unsaturated fatty acids, are also essential for prostate cancer growth and therapy resistance." (PMID 35127483, 2021). "In a mouse model, the authors compare HNF1B and ECI2 protein expression at different stages of prostate cancer development and concluded that during tumor progression, the protective effect of HNF1B is lost, and that is associated with an increased expression of ECI231." (PMID 32873863, 2020). "Recently, ACBD2/ECI2 was found to be significantly up-regulated in prostate cancer." (PMID 32044385, 2020). "Increased ECI2 expression predicts mortality in prostate cancer patients (p = 0.0086)." (PMID 28415728, 2017). "Since ECI2 was over-expressed in prostate cancer patient samples, we tested whether the enzyme is important for prostate cancer cell growth by following cell proliferation using life-cell imaging." (PMID 28415728, 2017). "Indeed, prostate cancer cells were unable to respond to ECI2 knockdown induced metabolic stress, which resulted in cell death activation (PARP cleavage)." (PMID 28415728, 2017). "However, the specific interaction between HNF1B and ECI2 is uncertain, but according to recent data, the increased gene expression of ECI2 may promote prostate cancer growth." (PMID 32873863, 2020). "ECI2 knockdown induced prominent accumulation of the canonical autophagy marker LC3, in two prostate cancer cell lines, LNCaP and VCaP." (PMID 28415728, 2017). "Based on these data, ECI2, or more generally, lipid degradation, might represent a novel drug target to limit prostate cancer cell proliferation." (PMID 28415728, 2017).
dyslipidemia (1 paper, 2022). "The results of gene chip sequencing showed that the expression of XLOC-005590 and HNF1A-AS1 was upregulated in obese T2DM patients with dyslipidemia compared with that in healthy volunteers, and the downstream ECI2 expression was significantly downregulated." (PMID 35957821, 2022).
glioma (1 paper, 2024). A benign or malignant brain and spinal cord tumor that arises from glial cells (astrocytes, oligodendrocytes, ependymal cells). "This study revealed five genes associated with the prognosis of glioma (ECI2, MCCC2, OXCT1, SUCLG2, and CPT2), providing novel insights into individualized treatment and prognosis." (PMID 39491527, 2024). "Five genes associated with the prognosis of glioma (ECI2, MCCC2, OXCT1, SUCLG2, and CPT2) were revealed and then, validated using glioma tissues, providing novel insights into individualized treatment and prognosis." (PMID 39491527, 2024). "ECI2, MCCC2, OXCT1, SUCLG2, and CPT2 were identified as prognostic genes for glioma." (PMID 39491527, 2024).
neuroblastoma (1 paper, 2024). Neuroblastoma (NB) is the most common solid, extracranial childhood tumor. "It is worth noting that 2 of 19 genes, ECI2 and TMCO3, clearly exhibited tumor-suppressive potential in neuroblastoma patients, with their low expressions correlated with poorer patient survival in both datasets." (PMID 39457392, 2024).
cancer (6 papers, 2015 to 2024). A tumor composed of atypical neoplastic, often pleomorphic cells that invade other tissues. "We have so far shown that ECI2 knockdown inhibits cancer cell proliferation, which is associated with decreased glucose consumption and lipid accumulation." (PMID 28415728, 2017). "The mRNA expression level of FXYD3, LGALS4, USH1C, ECI2, TGM2, and HMGA2 genes which are involved in EMT, drug resistance, and cancer progression were measured in HCT116/OX-R4.3 and HCT116/OX-R10 cells by qRT-PCR." (PMID 37535601, 2023). "Notably, the expression of ECI2, MCCC2, SUCLG2, and CPT2 was higher and that of OXCT1 was lower in cancer tissues than in para‐cancer tissues." (PMID 39491527, 2024). "Interestingly, here we observed that inhibition of ECI2 expression and perhexiline treatment led to prominent accumulation of lipids into cells, which did not promote cancer cell proliferation." (PMID 28415728, 2017). "Briefly, the expression of HNF1B and ECI2 mRNA was not statistically significantly different between the carcinoma and hyperplasia group (HNF1B: U = 278.0, Z = 1.51, p = 0.131; ECI2: U = 261.0, Z = 1.77, p = 0.078), although both genes showed a lower expression in AH." (PMID 32873863, 2020).
tumor (6 papers, 2017 to 2025). "Functional enrichment analysis indicates that ECI2 is inversely associated with several tumor proliferation signaling pathways, including PI3K/AKT, Wnt, and TNF signaling pathways." (PMID 40432805, 2025). "Recently, it has been shown in an animal model that the downregulation of HNF1B protein levels during tumor progression is associated with the upregulation of enoyl-CoA-(Δ) isomerase 2 (ECI2), which is one of the possible downstream targets of HNF1B31." (PMID 32873863, 2020). "Western blot and RT-PCR experiments demonstrated that both protein and mRNA expression levels of ECI2 were significantly reduced in tumor tissues." (PMID 40432805, 2025). "Analysis of TCGA transcriptome data revealed that ECI2 was significantly downregulated in various tumor tissues, including ccRCC." (PMID 40432805, 2025). "Western blot and PCR analyses confirmed the expression levels of the ECI2 in ccRCC, while lentiviral transduction was used to investigate the effects of ECI2 expression on tumor biological behaviors." (PMID 40432805, 2025). "Subsequently, we assessed the differential expression of ECI2 across ccRCC tumor cell lines, revealing significant reductions in the 786O and OS-RC-2 cell lines." (PMID 40432805, 2025). "Additionally, we conducted an in-depth exploration of ECI2's differential expression and functional analysis and verified the impact of ECI2 overexpression on the functionality of ccRCC tumor cells." (PMID 40432805, 2025). "ECI2, PPT2, ACSM3, PMVK, and IDO1 were low expressed in the prognosis of high-risk patients, which may be tumor suppressor factors." (PMID 37256178, 2023). "Subsequently, we examined the protein expression levels of ECI2 using CPTAC data, revealing a decrease in both total and phosphorylated protein levels of ECI2 within tumor tissues." (PMID 40432805, 2025).
cardiovascular disease (1 paper, 2025). "Furthermore, ECI2, KLK7, and SPINK6 appear to be linked to other forms of cardiovascular disease rather than CIHD." (PMID 41283645, 2025).
ECI2 also shares sentences with these, for which no sentence is quoted: breast carcinoma (2 papers); colorectal cancer (2); acquired aplastic anemia (1); alcoholic liver diseases (1); Clear Cell Renal Cell Carcinoma (1); colon cancers (1); coronary artery disease (1); fatty liver (1); infection (1); renal carcinoma (1).